INS (insulin)
Diseases named in the same sentence as INS in open-access papers (continued):
Sharing a sentence is not in itself a finding about the gene and the disease.
type 2 diabetes (continued). "Although the pathogenesis of type 2 diabetes, which is the most common form of the disease, has not yet been fully elucidated, the combination of insulin resistance in peripheral tissues and impairment of insulin secretion from pancreatic islets is considered a principal cause." (PMID 27115357, 2016). "On the other side, inositol imbalance might be partially explained with epimerase function failure: in fact, in a rat model of type II diabetes, conversion from MI to DCI in insulin-sensitive tissues was found to be reduced from 20 to 30% to 5% compared to normal rats." (PMID 27579037, 2016). "As insulin and IGF-II are the ligands for IR and their levels and/or availability may be increased in men with PCa who are obese or have type 2 diabetes: we also assessed alterations in IR isoforms following exposure to these agents in both concentrations of glucose in DU145 cells." (PMID 27733843, 2016). "This implies that, while exercise training did not reveal significant improvements in insulin sensitivity in our modest study sample, it may attenuate the natural progression of type 2 diabetes and its complications in this adolescent cohort." (PMID 26887327, 2016). "However, there was no study about assessment of the initial insulin dosage in new onset Chinese patients with type 2 diabetes." (PMID 26697503, 2016). "As a novel insulin secretagogue mechanism, it is important to determine whether GPR142 agonists stimulate insulin secretion only in the presence of high ambient glucose, which is essential for a desired safety profile for the treatment of type 2 diabetes." (PMID 27104960, 2016). "Muscle DG(18:0_20:4), DG(16:0_16:0), and DG(18:0_18:0) were increased in type 2 diabetes compared with nondiabetic individuals with similar obesity and lean athletes 7, and muscle Cer(d18:1/16:0) and Cer(d18:1/18:0) were increased in insulin‐resistant versus insulin‐sensitive women with obesity." (PMID 26916476, 2016). "However, another study conducted in type 2 diabetic patients has reported that plasma adrenaline response to recurrent hypoglycaemia was significantly reduced only in the nondiabetic control group but not in insulin treated type 2 diabetes patients." (PMID 27843452, 2016). "Moreover, type 2 diabetes is not characterized by the lack of insulin but in the inability of the body to use it properly; therefore, type 2 diabetes is also called insulin insensitivity." (PMID 27775605, 2016). "In type 2 diabetes, basal insulin levels are raised, but there is an absence of the immediate and major insulin release after meals that could confer local growth-promoting effects of the hormone." (PMID 27179658, 2016). "Elevation of 2 h PG and FPG levels are regulated by insulin secretory capacity and insulin sensitivity, but it is still controversial which factors are responsible for initial elevation of 2 h PG and FPG levels in the early stage development of type 2 diabetes." (PMID 26788515, 2016). "The current meta-analysis was performed to assess whether there might be any cardiovascular risk associated with a novel hepato-preferential basal insulin (based on less peripheral insulin effects) when compared to conventional insulins (glargine and NPH) in patients with type 1 or type 2 diabetes." (PMID 27188479, 2016). "The authors, studying type 2 diabetes patients in a randomized controlled trial setting, compared once daily and twice daily intermediate acting insulin (neutral protamine Hagedorn or Lente insulin), with or without oral drug." (PMID 25874190, 2015). "For example, in several studies, insulin therapy with detemir resulted in less weight gain and a lower rate of hypoglycemia compared to therapy with glargine among patients with type 2 diabetes, suggesting that detemir may not be as potent as glargine." (PMID 26120575, 2015).
type 2 diabetes (continued). "Our study is the first to demonstrate that SGLT2i exerts anti-atherogenic effects by the normalization of blood glucose levels in both mouse models of type 1 and type 2 diabetes through suppressing macrophage foam cell formation; this is independent of insulin action." (PMID 26606676, 2015). "Acarbose-like drugs that inhibit the α-glucosidases present in the epithelium of the small intestine, have been shown to decrease postprandial hyperglycemia and to improve impaired glucose metabolism without promoting insulin secretion in noninsulin dependent diabetes mellitus (NIDMM) patients." (PMID 26649063, 2015). "A recent study involving patients with type 2 diabetes showed that elevated DNA methylation of the insulin gene promoter, particularly at the cAMP response element (CRE) site, was proportional to HbA1c levels and inversely proportional to insulin gene expression." (PMID 25658116, 2015). "Furthermore, insulin treatment in patients with type 2 diabetes induces a reduction in liver fat rather than an increase." (PMID 25725623, 2015). "Also, the results show a consistent lower stimulated C-peptide secretion in those patients with LADA with or without insulin-treatment with respect to the respective counterparts with type 2 diabetes." (PMID 25572256, 2015). "Our results showed that administration of alpha-tocopherol alone could not induce any detectable change on the fasting insulin or HOMA-IR% in type 2 diabetes patients." (PMID 26693410, 2015). "This indicates that in type 2 diabetes, intensive insulin treatment is not suited for all patients." (PMID 26152221, 2015). "Consistent with this concept is the observation that an elevation of the circulating FFA concentration in lean healthy humans causes endothelial dysfunction, which is similar to that observed in obese individuals with reduced insulin sensitivity, and with or without type 2 diabetes." (PMID 27123439, 2015). "These earlier studies also do not specify whether and how (i.e., self-report vs. blood test) individuals were screened for prediabetes or type 2 diabetes and none quantified β-cell function, insulin sensitivity, or insulin secretion." (PMID 26192187, 2015). "Surprisingly, all studies having actually assessed muscle insulin sensitivity by hyperinsulinemic-euglycemic clamps failed to report any muscle insulin resistance in healthy individuals after 1–4 weeks on a high-fructose diet or in subjects with type 2 diabetes after 3 months." (PMID 26104800, 2015). "Likewise, a reduction in CFR was observed in patients with established type 2 diabetes, but not in insulin resistant patients." (PMID 26576929, 2015). "However, endothelial dysfunction has been observed also in non-obese type 2 diabetes models and insulin-induced relaxation was significantly decreased in the ob/ob aortas." (PMID 26098416, 2015). "Interestingly, there was a negative relationship with insulin sensitivity in non-diabetics but no (tendency for positive) relationship in drug naïve patients with type 2 diabetes." (PMID 26439389, 2015). "It is also approved for use as combination therapy with metformin, a sulfonylurea, a thiazolidinedione, or insulin, when these agents alone, with diet and exercise, do not provide adequate glycemic control in adults with type 2 diabetes (United States and European Union)." (PMID 24565221, 2014). "In accordance with the results of islet studies of GK rats and patients with type 2 diabetes, reduced gene expression levels of Glut2 and SNARE proteins were observed in SDG-P islets, suggesting impairments in glucose uptake and exocytosis machinery of the insulin granules in β cells." (PMID 24454742, 2014). "Studies on mammalian systems have shown that glucose accumulation within the cell might depend on either lack of insulin (type-1 diabetes) or defects in the insulin-signaling pathway (type-2 diabetes)." (PMID 24651653, 2014). "Rats with dexamethasone-induced type 2 diabetes do not have sufficient insulin." (PMID 24438349, 2014).
type 2 diabetes (continued). "Because adiponectin exerts a potent insulin-sensitizing effect by promoting the activation of AMP-activated protein kinase and PPARα in the liver and skeletal muscle, adiponectin may be a novel and promising therapeutic strategy for type 2 diabetes." (PMID 24845824, 2014). "Mice lacking the PTP-1B have enhanced insulin sensitivity which certifies that the inhibition activity of PTP-1B could be a novel way of treating type 2 diabetes and obesity." (PMID 25542373, 2014). "In WESDR, the incidence of macular edema after 10 years of development is of 20% in patients with diabetes mellitus type I, 25.4% in patients with type II diabetes insulin resistant and 13.9% of the patients with diabetes mellitus type II without insulin requirements." (PMID 25870678, 2014). "Well-controlled type 2 diabetes patients have intact GLP-1 response to glutamine ingestion and glutamine (30 g) or glutamine (15 g) in combination with the DPP-4 inhibitor sitagliptin (100 mg) decreases postprandial glycaemia and increases circulating insulin and GLP-1 when administered with a meal." (PMID 25412338, 2014). "Pharmacological administration of recombinant FGF21 increases energy expenditure, glucose tolerance, and insulin sensitivity and decreases adiposity, hyperlipidemia, and hepatic triacylglycerol accumulation in rodent and non-human primate models of obesity and type 2 diabetes." (PMID 24733293, 2014). "The majority of care for people with type 2 diabetes occurs in general practice, however when insulin initiation is required it often does not occur in this setting or in a timely manner and this may have implications for the development of complications." (PMID 24479762, 2014). "Furthermore, serum betatrophin protein was positively correlated with fasting glucose, insulin and BMI in patients with type II diabetes but not with levels of triacylglycerol, total cholesterol, HDL cholesterol and LDL cholesterol." (PMID 25530616, 2014). "The basis of the insulin secretory effect in type 2 diabetes is still not fully understood." (PMID 24705605, 2014). "Testing of rapamycin in combination with insulin sensitizers is warranted, as such compounds may ameliorate the putative negative effects of rapamycin in the type 2 diabetes environment." (PMID 25473963, 2014). "Similarly, leptin treatment did not have a clinically important effect on insulin action in obese people with newly diagnosed type 2 diabetes." (PMID 24987413, 2014). "Low SHBG concentrations have been shown to predict the development of type 2 diabetes, independent of glucose and insulin, in premenopausal women and may play a role in its pathogenesis." (PMID 23936766, 2013). "Moreover, Pima Indians with the Gly/Gly genotype had lower levels of insulin secretion following glucose loading, suggesting that the PGC-1α gene could be a candidate gene for type II diabetes." (PMID 24109487, 2013). "Third, biochemical markers for type 2 diabetes (fasting glucose, insulin, lipids, and HbA1C, etc.)were not available in the full NHS cohorts, and thus could not be adjusted in the models." (PMID 23427333, 2013). "However, the role of miRNAs in insulin secretion and type 2 diabetes has not been exhaustively studied." (PMID 24109547, 2013). "Technological advancements in insulin such as “patch-pumps” which do not need an external catheter, could improve patients’ acceptance and therefore clinical outcomes also in type 2 diabetes." (PMID 24348585, 2013). "Thus, drugs which improve insulin sensitivity without adverse effects were reported to be useful for the long-term treatment in type 2 diabetes." (PMID 23936668, 2013). "Survey among 2215 well-controlled type 2 diabetes patients (not using insulin, HbA1c ≤58 mmol/mol, systolic blood pressure ≤145 mmHg and total cholesterol ≤5.2 mmol/l) who participated in the EFFIMODI study, a randomised controlled patient-preference equivalence trial." (PMID 23899039, 2013).
type 2 diabetes (continued). "Metformin has been widely used for treating type 2 diabetes without stimulating insulin production." (PMID 23781268, 2013). "Although time to insulin initiation was not taken into account, a small primary care study (n = 152) suggested that people with type 2 diabetes switching to insulin therapy were 14-times more likely to have co-morbid depression than those individuals who did not start insulin." (PMID 24223860, 2013). "For diabetic individuals, especially in parents where we did not know time to insulin treatment, we could not distinguish between type 1 and type 2 diabetes." (PMID 24336895, 2013). "Our study did not indicate whether the MBL2 gene influences type 2 diabetes by affecting insulin secretion or insulin action." (PMID 24376633, 2013). "For these studies, nondiabetic control and type 2 diabetic ob/ob mice were challenged with an intrathecal injection of insulin or insulin-like growth factor 1 (IGF-1) and downstream signaling was evaluated in the DRG and sciatic nerve using Western blot analysis." (PMID 24252636, 2013). "Provided that most of the antidiabetic agents are associated with weight gain and the vast majority of patients with type 2 diabetes are overweight or obese, the introduction of SGLT2 inhibitors with an insulin independent mechanism could have a pivotal role in the management of type 2 diabetes." (PMID 24341330, 2013). "In Londrina, 87% of PCPs directly involved in the treatment of diabetic patients reported at least one difficulty or insecurity with insulin use, and 38% admitted that they would not initiate insulin for a hypothetical patient with type 2 diabetes who was clearly in need of insulin initiation." (PMID 23612462, 2013). "However, the reduction in insulin sensitivity and mitochondrial function as observed in our type 2 diabetic patients was independent of intramyocellular lipid content, which was similar between the two groups." (PMID 23418416, 2013). "The low insulin requirement in both groups can be explained by our patients' BMI which was significantly less than described in other populations as well as by the adherence to MNT, as indirectly shown by the weight gain, and the short duration of disease for type 2 diabetes." (PMID 23840206, 2013). "In obese or hyperglycemic type 2 diabetic patients, circulating levels of AEA and 2-AG are increased and elevated levels of 2-AG are found in visceral adipose tissue, while hepatic Cb1r activation leads to impaired insulin sensitivity as well as reduced insulin clearance in mice." (PMID 23894352, 2013). "Glargine alone or in combination with fast acting insulin is more effective in reducing glycaemia than biphasic human insulin alone or in combination with fast acting insulin in patients with type 2 diabetes without increase in hypoglycaemic episodes or body weight." (PMID 23916120, 2013). "Therefore, to improve the glycemic control in type-2 diabetes more effectively, the simultaneous treatment with BDNF and the drug having a function to alleviate impaired insulin secretion might be required." (PMID 24106476, 2013). "Furthermore, from a public health perspective, the majority of people with type 2 diabetes are receiving oral antidiabetes drugs without insulin." (PMID 23121373, 2013). "A previous study in 2003 among young diabetes type 2 patients (<18 years old) found that 42.9% of patients did not receive any medication, 28.6% received insulin and OAD combination therapy, and 14.3% received insulin monotherapy and another 14.3% received OAD monotherapy." (PMID 24299164, 2013). "C2C12 myotubes and the KK-Ay murine model of type 2 diabetes were used to evaluate the effect of PMI5011 on steady-state levels of ubiquitylation, proteasome activity and expression of Atrogin-1 and MuRF-1, muscle-specific ubiquitin ligases that are upregulated with impaired insulin signaling." (PMID 23437325, 2013).
type 2 diabetes (continued). "Therefore, drugs that ameliorate the insulin resistance without stimulating insulin release from β-cells have been developed for the treatment of type 2 diabetes." (PMID 25379289, 2013). "However, those recorded insulin-treated have for the most type 1 diabetes and those with non-insulin treated type 2 diabetes." (PMID 23837500, 2013). "Why is it that insulin treatment may induce insulin dependency in Japanese type 2 diabetes patients, but not in others?" (PMID 22567309, 2012). "In conclusion, lixisenatide administered once daily as an add-on treatment to basal insulin with or without a sulfonylurea in Asian patients with type 2 diabetes and FPG at screening <250 mg/dl provided a significant improvement in HbA1c and a pronounced effect on postprandial glucose control." (PMID 22564709, 2012). "In this cohort, we have previously reported that individuals with a family history of type 2 diabetes (FH+) exhibited similar insulin sensitivity, fasting blood glucose and plasma insulin at baseline to age, and fatness matched individuals without a family history of type 2 diabetes (FH-)." (PMID 22586466, 2012). "The Matsuda composite index of insulin sensitivity were lower in participants having IGT and type 2 diabetes compared to NGT, whereas we found a compensatory higher beta-cell function (HOMA-B and insulinogenic index) in the individuals with impaired glucose tolerance compared to type 2 diabetes." (PMID 23251434, 2012). "However, the infusion of TNF-α-neutralizing antibodies into obese, insulin-resistant subjects, or type 2 diabetic patients, did not improve insulin sensitivity." (PMID 22110480, 2012). "Whereas the effects of TZD on lipids are well known, the effects of insulin on lipids are not generally appreciated; in fact, insulin therapy has been hypothesized to have deleterious effects on lipids in patients with type 2 diabetes." (PMID 22081557, 2012). "We present the results of a study that assessed the effects on glycaemic control of lixisenatide in comparison to placebo as an add-on treatment to basal insulin with or without sulfonylurea in terms of HbA1c reduction over a period of 24 weeks in Asian patients with type 2 diabetes." (PMID 22564709, 2012). "Thus, in one prospective study, 323 patients with type 2 diabetes uncontrolled on metformin plus liraglutide (baseline HbA1c, 7.6%) were randomised to add-on insulin detemir (n = 162) or continuation without insulin detemir (n = 161)." (PMID 23061886, 2012). "Similar findings have been shown in type 2 diabetic patients, in whom a positive effect on glycemia was clearly revealed after grape seed extract ingestion, but this did not result in statistically significant changes in blood insulin levels." (PMID 22479589, 2012). "Similarly, an acute but short-term CR without malnutrition has been effective in the care of type II diabetes by improving insulin-stimulated glucose uptake in humans." (PMID 22479589, 2012). "Furthermore, they are more insulin-resistant, as a group, than matched control subjects without a family history of type 2 diabetes." (PMID 22992414, 2012). "It is worth mentioning that the GIP level in patients suffering from type 2 diabetes is similar to the one in healthy people, however, for unknown reasons, it does not influence blood glucose and insulin level." (PMID 22462016, 2012). "Finally, although we did not detect seizures or coma after i.p. insulin administration, the possible appearance of these symptoms in fasted animals should be taken into account." (PMID 23056516, 2012). "However, in most of these studies the focus is mainly on patients with type 2 diabetes, not treated with insulin." (PMID 22397638, 2012). "Our group has found that punicic acid ameliorates type 2 diabetes-induced inflammation by activating PPARγ and PPARα, and repressing TNF-α expression in white adipose tissue and liver and increases peripheral insulin sensitivity without causing any adverse side effects." (PMID 21904603, 2011).